SNAP29 (synaptosome associated protein 29)
Description:
SNAREs, soluble N-ethylmaleimide-sensitive factor-attachment protein receptors, are essential proteins for fusion of cellular membranes. SNAREs localized on opposing membranes assemble to form a trans-SNARE complex, an extended, parallel four alpha-helical bundle that drives membrane fusion. SNAP29 is a SNARE involved in autophagy through the direct control of autophagosome membrane fusion with the lysososome membrane. Also plays a role in ciliogenesis by regulating membrane fusions.
Synonyms: SNAP-29; CEDNIK
Tractability: Antibody: UniProt places it where antibodies can reach, with high confidence; its Gene Ontology location is reachable by antibodies, with high confidence. PROTAC: ubiquitination databases record sites on it; its protein half-life has been measured.
Gene: Protein-coding gene on chromosome 22 (20,858,537 to 20,891,214, forward strand). Ensembl gene ENSG00000099940.
Subcellular location: Cytoplasm; Golgi apparatus membrane; Cytoplasmic vesicle, autophagosome membrane; Cell projection, cilium membrane
Subcellular location (Human Protein Atlas): Cytosol; Centrosome
Pathways (Reactome):
Immune System: Neutrophil degranulation
Vesicle-mediated transport: Intra-Golgi traffic
Gene Ontology:
Molecular function: protein binding; SNARE binding; SNAP receptor activity; syntaxin binding
Biological process: autophagosome maturation; autophagosome membrane docking; cilium assembly; cellular response to starvation; exocytosis; macroautophagy; membrane fusion; synaptic vesicle fusion to presynaptic active zone membrane; synaptic vesicle priming; vesicle fusion
Cellular component: ciliary pocket membrane; cytoplasm; cytosol; mitochondrion; SNARE complex; autophagosome; autophagosome membrane; azurophil granule membrane; Golgi membrane; lysosomal membrane; membrane fusion priming complex; plasma membrane; ciliary membrane; presynapse
Genetic constraint (gnomAD): Loss-of-function variants: 10 observed, 20.36 expected, observed/expected ratio (o/e) 0.49, 90% interval 0.3 to 0.83. The upper end of that interval is the gene's LOEUF score, 0.83, which puts it in group 3 of 6, group 1 being the genes least tolerant of losing a copy. Missense variants: 314 observed, 302.29 expected, observed/expected ratio (o/e) 1.04, 90% interval 0.95 to 1.14. Synonymous variants: 109 observed, 113.93 expected, observed/expected ratio (o/e) 0.96, 90% interval 0.82 to 1.12.
Homologues: Orthologues: chimpanzee SNAP29 (99% identical), rabbit SNAP29 (89% identical), guinea pig SNAP29 (86% identical), dog SNAP29 (86% identical), pig SNAP29 (84% identical), rat Snap29 (84% identical), mouse Snap29 (84% identical), tropical clawed frog snap29 (55% identical), zebrafish snap29 (45% identical), Drosophila melanogaster Snap29 (30% identical), Caenorhabditis elegans snap-29 (26% identical). Paralogues in human: SNAP47 (23% identical), SNAP23 (18% identical), SNAP25 (17% identical).
Diseases named in the same sentence as SNAP29 in open-access papers:
SNAP29 is named in the same sentence as 63 diseases in open-access papers, as found by Europe PMC text mining. Sharing a sentence is not in itself a finding about the gene and the disease. The quoted sentences say what the papers report.
CEDNIK syndrome (13 papers, 2008 to 2025). CEDNIK syndrome is a neurocutaneaous syndrome characterized by severe developmental abnormalities of the nervous system and aberrant differentiation of the epidermis. "Our patient underwent molecular genetic testing in the form of whole exome sequencing (WES), which confirmed a genetic mutation in SNAP29, consistent with a diagnosis of CEDNIK syndrome." (PMID 40709160, 2025). "Pathogenic variants in the SNAP29 gene cause CEDNIK syndrome (MIM 609528), with an autosomal recessive pattern of inheritance." (PMID 40709160, 2025). "Our study reveals the role of Snap29 in the maintenance of ESC pluripotency and provides insights for further investigation of the complicated pathogenic mechanisms of CEDNIK syndrome caused by Snap29 deficiency." (PMID 36614195, 2023). "In humans, inactivating SNAP29 mutations causes CEDNIK syndrome, a rare multi-systemic disorder characterized by congenital neuro-cutaneous alterations." (PMID 33718375, 2021). "Loss-of-function mutations in the synaptosomal-associated protein 29 (SNAP29) lead to the rare autosomal recessive neurocutaneous cerebral dysgenesis, neuropathy, ichthyosis, and keratoderma (CEDNIK) syndrome." (PMID 34069872, 2021). "Within the previously defined autozygous region predicted to contain the causative mutation, in addition to the described TUBA8 loss of function mutation, we identified a mutation in SNAP29, previously identified as the cause of CEDNIK syndrome." (PMID 28388629, 2017). "Loss of functional SNAP29 results in CEDNIK syndrome (Cerebral Dysgenesis, Neuropathy, Ichthyosis and Keratoderma)." (PMID 20305790, 2010). "Our results are consistent with the recent description of a mutation in SNAP29, a regulator of vesicle fusion to target membrane, found in CEDNIK syndrome." (PMID 19057675, 2008). "In humans, the loss of functional Snap29 results in CEDNIK syndrome (cerebral dysgenesis, neuropathy, ichthyosis, and keratoderma), a neurocutaneous disease characterized by severe developmental abnormalities of the nervous system and aberrant differentiation of the epidermis." (PMID 36614195, 2023). "Our comprehensive analysis of Snap29−/− mutant mice reveals that many more abnormalities associated with CEDNIK syndrome are modeled in this mutant mouse line and clearly indicate that the genetic background does contribute to the expressivity and the penetrance of Snap29 mutations in the mouse." (PMID 31633066, 2019). "We next investigated the defects caused by loss of Snap29 to test whether they correlate with loss of previously characterized Snap29 functions and whether they reproduce CEDNIK syndrome traits." (PMID 30718891, 2019). "To understand whether zebrafish could represent a suitable model organism for human CEDNIK syndrome, we first analyzed protein sequence conservation of zebrafish Snap29 with its human homolog." (PMID 30718891, 2019). "CEDNIK syndrome was found to be caused by a 1-bp deletion in the SNAP29 gene, resulting in the absence of the protein." (PMID 20305790, 2010). "The discovery that CEDNIK syndrome results from absence of SNAP29 provided us with the means to study the biological role of this protein." (PMID 20305790, 2010). "Our ESC model lacking Snap29 may serve as a powerful tool for investigating the embryonic differentiation process of CEDNIK syndrome and seeking compounds that might ameliorate traits of the disease." (PMID 36614195, 2023).
ichthyosis (11 papers, 2008 to 2025). Disorders of cornification that are characterized by visible scaling and/or hyperkeratosis of most or all of the skin. "Recently, a mutation in a SNARE protein (SNAP29) was associated with cerebral dysgenesis, neuropathy, ichthyosis and palmoplantar keratoderma (CEDNIK)." (PMID 19057675, 2008). "Mutations in SNAP29 disrupt normal cellular processes, resulting in a broad spectrum of clinical manifestations, including facial dysmorphisms, microcephaly, severe developmental delay, hypotonia, ichthyosis, and peripheral neuropathy." (PMID 40709160, 2025). "Homozygous mutations in SNAP29, encoding a SNARE protein mainly involved in membrane fusion, cause CEDNIK (Cerebral Dysgenesis, Neuropathy, Ichthyosis and Keratoderma), a rare congenital neurocutaneous syndrome associated with short life expectancy, whose pathogenesis is unclear." (PMID 30718891, 2019). "Indeed, homozygous inactivating mutations in the human SNAP29 gene are responsible for Cerebral Dysgenesis, Neuropathy, Ichthyosis, palmoplantar Keratoderma (CEDNIK; OMIM # 609528), a rare autosomal recessive syndrome characterized by congenital neurological and dermatological alterations." (PMID 30718891, 2019). "Patients with homozygous mutations in SNAP29 are responsible for CEDNIK (cerebral dysgenesis, neuropathy, ichthyosis, and keratoderma) syndrome, which has a number of clinical manifestations, some of which overlap with those found in 22q11.2 deletion syndrome." (PMID 33482818, 2021). "Snap29 homozygous mutant mice on the C57Bl/6 genetic background exhibited ichthyosis and died at birth due to a failure in skin barrier formation." (PMID 31633066, 2019). "Moreover, bi-allelic SNAP29 mutations in patients are responsible for CEDNIK (cerebral dysgenesis, neuropathy, ichthyosis, and keratoderma) syndrome." (PMID 31633066, 2019).
neuropathy (10 papers, 2008 to 2025). A disorder affecting the nervous system that manifests with pain, tingling, numbness, and/or muscle weakness. "Snap29 mutant zebrafish larvae have shown skin defects comparable to cerebral dysgenesis, neuropathy, ichthyosis and keratoderma (CEDNIK) disease caused by the homologous SNAP29 gene variants in humans." (PMID 36768619, 2023).
schizophrenia (10 papers, 2008 to 2024). A major psychotic disorder characterized by abnormalities in the perception or expression of reality. "Genetic studies have linked a specific allele polymorphism and copy number variants of SNAP29 to neuropsychiatric disorders such as schizophrenia." (PMID 37108604, 2023). "As an example, genetic variations in SNAP-29 are also linked with neurodevelopment disorders as observed in 22q11.2 deletion syndrome (di George syndrome) which is linked with schizophrenia and bipolar disorder." (PMID 33833673, 2021). "Otherwise, other genes in this region seem to be responsible for a more particular phenotype: certain SNP haplotypes within genes PIK4CA and SNAP29 have been recently suggested to confer a higher risk of developing schizophrenia." (PMID 19490635, 2009). "VWA8 has been linked to neurological disorders such as autism and bipolar disorder in various genome-wide associated studies, while SNAP29 has been proposed as a candidate of genetically based psychiatric disorders such as schizophrenia and bipolar disorder in previous studies." (PMID 39727940, 2024). "Whereas SNAP29 has been found to negatively modulate neurotransmitter release and contributes to schizophrenia and autism spectrum disorder." (PMID 33482818, 2021). "In the same direction association studies have reported several genes of this region associated with risk to develop schizophrenia and bipolar disorder, including PRODH, COMT, ZNF74, PCQAP, UFD1L, ZDHHC8, DGCR2 and SNAP29." (PMID 18284679, 2008). "Such evidence and that linking Snap29 to secretion and synaptic transmission (see previous chapter) suggest that Snap29 might act in trafficking processes subverted in schizophrenia." (PMID 31225470, 2018). "Could schizophrenia involve an alteration of SNAP29 gene activity?" (PMID 31225470, 2018). "Clarity on the molecular nature of the complexed formed by Snap29 will also aid to understand its role in synaptic transmission, which is likely relevant to the pathogenesis of CEDNIK and perhaps Schizophrenia." (PMID 31225470, 2018).
22q11.2 deletion syndrome (5 papers, 2015 to 2021). 22q11.2 deletion syndrome (DS) is a chromosomal anomaly which causes a congenital malformation disorder whose common features include cardiac defects, palatal anomalies, facial dysmorphism, developmental delay and immune deficiency. "One study of note analysed SNAP29 in patients with atypical clinical presentations of 22q11.2 deletion syndrome and found hemizygous mutations in 4 of 17 cases, of which two had PMG and microcephaly." (PMID 25855803, 2015). "No significant hemizygous changes were identified either in PI4KA or in SNAP29, another gene implicated in brain-related phenotypes associated with 22q11.2 deletion syndrome." (PMID 25855803, 2015). "An exome study of 22q11.2 deletion syndrome patients revealed novel mutations in the remaining copy of SNAP29, suggesting that hemizygous mutations might unmask a recessive CEDNIK-like condition contributing to the phenotypic variety of patients." (PMID 31225470, 2018). "SNAP29 maps to the 22q11.2 region and is deleted in 90% of patients with 22q11.2 deletion syndrome (22q11.2DS)." (PMID 31633066, 2019). "SNAP29 was reported to be abnormal in 90% of patients with 22q11.2 deletion syndrome." (PMID 33482818, 2021).
Obesity (5 papers, 2019 to 2025). Accumulation of substantial excess body fat. "Some of these SNP loci were linked to genes, such as Wsb1, Snap29 and Aplp2, suggesting that they play a role in obesity development." (PMID 32273571, 2020). "The immunohistochemistry of adipose tissue showed decreased STX17 and SNAP29 puncta in obesity-related SAP mice." (PMID 40806352, 2025). "The results showed that the expression of STX17 and SNAP29 in adipose tissue significantly decreased after the induction of obesity and SAP." (PMID 40806352, 2025). "Immunofluorescence for STX17 or SNAP29 co-staining with F4/80 indicated a lower average expression of STX17 or SNAP29 in ATMs of the obesity-related SAP group." (PMID 40806352, 2025). "Western blot and qPCR analyses demonstrated that both the induction of obesity and SAP reduced the protein or mRNA levels of STX17 and SNAP29 in adipose tissue." (PMID 40806352, 2025).
autism (4 papers, 2019 to 2024). Persistent deficits in social interaction and communication and interaction as well as a markedly restricted repertoire of activity and interest as well as repetitive patterns of behavior. "Additional functional studies are necessary, to evaluate the role of SNAP29 in autism and the consequence of other genes expressed in LCR22 B-D in neurodevelopmental phenotypes." (PMID 33482818, 2021). "Intriguingly, we noticed that the 3 patients with only SNAP29 probe duplication in P245 assay, who were confirmed to have nested atypical duplications from C-D or B-D in P250 assay, presented with language delay, difficulty with social interactions and even autism." (PMID 33482818, 2021).
keratoderma (4 papers, 2008 to 2025). "Mutations in SNAP29 are associated in humans with CEDNIK (cerebral dysgenesis, neuropathy, ichthyosis, and keratoderma), a rare neuro-cutaneous syndrome whose pathogenesis is unclear." (PMID 33718375, 2021).
microcephaly (4 papers, 2019 to 2025). A congenital or acquired developmental disorder in which the circumference of the head is smaller than normal for the person's age and sex. "In addition, CEDNIK patients show signs of microcephaly and facial dysmorphism, hypoplastic optic disk, sensorineural deafness, and severe cachexia, indicating multisystem defects caused by Snap29 deficiency." (PMID 36614195, 2023).
Viral infection (4 papers, 2015 to 2025). "The association of Snap29 with viral infection is not limited to HPIV3." (PMID 31225470, 2018). "While the mechanism of SNAP29 regulation of EV-A71 is not yet clear, these two papers and the emerging notion that subversion of autophagy is a key step in the life cycle of viruses 61, 62, 63, indicates that SNAP29 might be a crucial factor to prevent virus infection." (PMID 31225470, 2018). "In addition, the recent identification of specific regulators of autophagosome maturation, such as syntaxin-17, SNAP29, and VAMP8, presents an exciting opportunity to further define the role of this critical autophagic process in limiting and/or enhancing viral infections." (PMID 25811485, 2015).
bipolar disorder (3 papers, 2008 to 2024). A disorder of the brain that causes unusual shifts in mood, energy, activity levels and the ability to carry out day-to-day tasks. "VWA8 and SNAP29 were significantly up-regulated in our analysis of the bipolar disorder datasets using the CASh method." (PMID 39727940, 2024). "VWA8 (von Willebrand domain-containing protein 8), SNAP29 (Synaptosomal-associated protein 29), RIF1 (Replication Timing Regulatory Factor 1), AQP4 (Aquaporin-4) and GSTM3 (Glutathione S-Transferase Mu 3) were some relevant differentially expressed genes detected in the bipolar disorder datasets." (PMID 39727940, 2024).
breast carcinoma (2 papers, 2023). "Recent evidence from a breast cancer cell line and a human melanoma cell line suggests that Snap29 plays a role in the TNFα-NF-κB-FOXP3 signaling axis, and silencing Snap29 promotes tumor cell migration." (PMID 36614195, 2023). "Furthermore, we found that SNAP29 depletion also reduced sEV release in the breast cancer cell lines MCF-7 and MDA-MB-231 and in the colorectal adenocarcinoma Caco-2 cells, when measured by NTA." (PMID 37285022, 2023).
Dengue (2 papers, 2020 to 2021). "Studies have shown that Dengue and enteroviral infections inhibit autophagic flux in host cells by decreasing p62 or cleaving SNAP29, respectively, to facilitate infection." (PMID 32511341, 2020).
Hyperkeratosis (2 papers, 2018 to 2019). Hyperkeratosis is a histopathological term defining a thickened stratum corneum and may be present in many different skin conditions, with many possible overlaps. "Epidermal deficiency of SNAP29 also causes hyperproliferation with acanthosis and hyperkeratosis, defects in epidermal differentiation, abnormal formation of LBs and reduced LB contents at the SG-SC junction." (PMID 29409756, 2018). "However, at P1—prior to onset of skin abnormalities and P3—when skin abnormalities were morphologically apparent, epidermis of Snap29−/− mutant pups showed hyperkeratosis and condensed stratum corneum." (PMID 31633066, 2019).
Atrophy (1 paper, 2019). Any weakening or degeneration, especially through lack of use. "As a subset of CEDNIK patients also show ophthalmological abnormalities such as optic nerve hypoplasia and atrophy, we used electroretinogram (ERG) to assess retinal function in 21 mice, including five wild type, eight Snap29+/− and eight Snap29−/− mutant mice." (PMID 31633066, 2019).
basal cell carcinoma (1 paper, 2021). A carcinoma involving the basal cells. "Since approximately 85% of basal cell carcinomas display mutations in the Shh pathway and around 73% of those are attributed to a mutation in Ptch1, the role of SNAP29 in basal cell carcinoma should be further investigated." (PMID 34069872, 2021).
Cerebral ischemia (1 paper, 2021). Restriction of arterial blood supply to the brain associated with insufficient oxygenation to support the metabolic requirements of the tissue. "Therefore, disruption of the function of SNAP29 was sufficient to cause cognitive impairment in mice after cerebral ischemia." (PMID 33754017, 2021).
cervical cancer (1 paper, 2026). A primary or metastatic malignant neoplasm involving the cervix. "Definitive genetic evidence is provided by studies in specific cancer models: re‐expression of an O‐GlcNAcylation‐defective SNAP‐29 mutant, but not wild‐type SNAP‐29, rescues the fusion block induced by arsenic in cervical cancer HeLa cells or by the cytotoxic compound SM15 in treated cancer cells." (PMID 41540817, 2026).
cognitive decline (1 paper, 2012). "It is tempting to speculate that genes such as PIK4CA and SNAP29 that are deleted in our patient may be involved in the emergence of psychotic "positive symptoms" while others, such as PRODH and COMT that are not deleted, play a role in the cognitive decline process." (PMID 23245648, 2012).